JAK2 (Janus kinase 2)
Diseases named in the same sentence as JAK2 in open-access papers (continued):
Sharing a sentence is not in itself a finding about the gene and the disease.
pulmonary fibrosis (36 papers, 2018 to 2026). Chronic progressive interstitial lung disorder characterized by the replacement of the lung tissue by connective tissue, leading to progressive dyspnea, respiratory failure, or right heart failure. "JAK2 is highly expressed in proliferative alveolar epithelial cells and fibroblast-like cells, and the JAK2 signaling pathway also plays a key role in idiopathic pulmonary fibrosis (IPF)." (PMID 41426608, 2025). "JAK2 mediates transforming growth factor β signaling in fibroblasts, and its activation is observed in lung fibrosis." (PMID 38456909, 2024). "Research on pulmonary fibrosis has demonstrated that JAK2/STAT3 signaling pathway activation is critical in inducing epithelial to mesenchymal and fibroblast to myofibroblast transitions." (PMID 38253716, 2024). "This regulatory role of JAK2 in the pathogenesis of pulmonary fibrosis was further demonstrated by the attenuation of bleomycin-induced murine pulmonary fibrosis using a JAK2-selective pharmacological inhibitor CEP33779." (PMID 38082233, 2023). "We also investigated one of the main inflammatory pathways induced by pulmonary fibrosis such as the JAK2/STAT3 pathway, to evaluate a possible mechanism of action underlying the beneficial effects of KYP-2047 on pulmonary fibrosis." (PMID 37626373, 2023). "In this study, we demonstrated the anti-pulmonary-fibrosis and anti-inflammatory effects of Fed through suppressing both JAK2/STAT3 and TGF-β1 signaling." (PMID 34361644, 2021). "In an animal model of bleomycin-induced lung fibrosis and PH, p-JAK2/p-STAT3 were overexpressed and localized in pulmonary arteries." (PMID 34067108, 2021). "We investigated one of the key inflammatory pathways induced by pulmonary fibrosis: JAK2/STAT3 and Ikb-α/NF-kB systems." (PMID 32660140, 2020). "Dual JAK2/STAT3 inhibition was more effective for inhibiting both of these cellular transitions and lung fibrosis than the individual inhibition of JAK2 or STAT3, which implies synergistic and independent roles of these proteins in pulmonary fibrosis." (PMID 32660140, 2020). "Dual JAK2/STAT3 inhibition was more effective for inhibiting both these cellular transitions and lung fibrosis than the individual inhibition of JAK2 or STAT3, which implies synergistic and independent roles of these proteins in IPF." (PMID 29409529, 2018). "Consistent with an independent role of p-JAK2 in lung fibrosis, we observed that p-JAK2 inhibition in ATII and lung fibroblasts from IPF patients partially reduced the mesenchymal-myofibroblast transformation induced by TGF-β1 and IL-6/IL-13." (PMID 29409529, 2018). "The JAK2/STAT3 pathway is activated in IPF, and treatment with JSI-124 (a dual inhibitor of JAK2/STAT3) decreases collagen deposition during lung fibrosis." (PMID 30524284, 2018). "In addition, the JAK2/STAT3 pathway is important for the development of pulmonary fibrosis in Mycobacterium tuberculosis infection." (PMID 39255287, 2024). "Similarly, selective JAK2 tyrosine kinase inhibition by fedratinib attenuated TGF-β- and IL-6-induced myofibroblast activation regulated by JAK2/p-STAT3 as well as reduced bleomycin-induced lung fibrosis in mice in vivo." (PMID 35626663, 2022). "Therefore, targeting JAK2/STAT3 signaling has been highlighted as a potential strategy for treating pulmonary fibrosis." (PMID 34361644, 2021). "However, the individual mechanisms by which JAK2 and STAT3 cause pulmonary fibrosis are currently unknown, and together with the mechanism underlying the synergistic effects of dual inhibition, remain to be determined in future research." (PMID 29409529, 2018). "JAK2/STAT3 is an important advocate of inflammation and fibrosis pathways, and inhibition of JAK2/STAT3 can reduce alveolar inflammation and pulmonary fibrosis in IPF patients." (PMID 41155944, 2025).
pulmonary fibrosis (continued). "We conclude that BIC reduces SiO2-induced pulmonary fibrosis by inhibiting the inflammatory fibrotic responses in silicosis via the TGF-β1/SMAD2/3 and JAK2/STAT3 signaling pathways." (PMID 39060930, 2024). "In contrast to previous findings, our results further supported the involvement of the α7nAChR-mediated JAK2/STAT3 pathway in the differentiation of Th17 cells, revealing a specific action of this pathway in regulating lung fibrosis." (PMID 37064881, 2023). "The dual inhibitor of JAK2 and STAT3, JSI-124, attenuated bleomycin-induced pulmonary fibrosis in vivo." (PMID 36671504, 2023). "Baricitinib attenuated bleomycin-induced skin and lung fibrosis in SSc-ILD mice model by targeting JAK2 and regulating of the crosstalk between the JAK2 and TGF-β1 signaling pathways." (PMID 37194022, 2023). "Previous studies found that the Janus kinase 2 (JAK2)/signal transducer and activator of transcription 3 (STAT3) signaling pathways are involved in idiopathic pulmonary fibrosis (IPF)." (PMID 35120332, 2022). "Recent studies have also confirmed that C-188-9 (a STAT3 inhibitor) and JSI-124 (a dual inhibitor of JAK2 and STAT3) decrease pulmonary fibrosis." (PMID 36055997, 2022). "The JAK2 and STAT3 mRNA transcript levels and protein expression were increased in the isolated pulmonary arteries of idiopathic fibrosis pulmonary (IPF) patients with PH." (PMID 34067108, 2021). "Genetic or pharmacologic inactivation of SHP2 promotes accumulation of JAK2 phosphorylated at Y570, reduces JAK2/STAT3 signaling, inhibits TGFβ-induced fibroblast activation and ameliorates dermal and pulmonary fibrosis." (PMID 30108215, 2018). "Interestingly, SPP1 regulates macrophage polarization toward the anti-inflammatory M2 phenotype via upregulation of the Janus kinase 2 (JAK2)/STAT3 signaling pathway, resulting in pulmonary fibrosis." (PMID 38919629, 2024). "JAK2 is a non-receptor tyrosine kinase activated by a broad spectrum of stimulators, which has been reported as the most predominant subform activated in lung fibrosis 35-37." (PMID 37064881, 2023). "Moreover, KYP-2047 was able to modulate the JAK2/STAT3 pathway, highly involved in pulmonary fibrosis." (PMID 37626373, 2023). "In RA-ILD presenting as UIP, Janus kinase 2/signal transducer and activator of transcription 3 (JAK2/STAT3) were identified as intermediary molecules of TGF-β in activating myofibroblasts promoting lung fibrosis." (PMID 36768729, 2023). "IL-6 was shown to be upregulated in IPF patients 43 and animal models of pulmonary fibrosis 44; furthermore, JAK2 and STAT3 were increased and activated in the hyperplastic alveolar cells of IPF patients 42, which suggested that IL-6/JAK/STAT3 plays a role in lung fibrosis." (PMID 36147459, 2022). "The levels of activated JAK2 and STAT3 were elevated in alveolar type II epithelial cells (ATII) and lung fibroblasts from patients with IPF, in which JAK2 and STAT3 participate in lung fibrosis by dependent and independent mechanisms." (PMID 35120332, 2022). "Thus, inhibition of downstream JAK2 and STAT3 signaling by JSI-124 reduced both pulmonary fibrosis and expression of these mediators in the lung." (PMID 29409529, 2018). "In rats administered JSI-124, a dual inhibitor of p-JAK2/p-STAT3, at a dose of 1 mg/kg/day, bleomycin-induced lung fibrosis was reduced and collagen deposition in the lung was inhibited, as were JAK2 and STAT3 activation and several markers of fibrosis, autophagy, senescence, and anti-apoptosis." (PMID 29409529, 2018). "The use of either the JAK2 inhibitor JSI-124 or small RNA interference of JAK2 inhibited the transition of pulmonary artery endothelial cells to fibroblasts in vitro, and in vivo models also confirmed that JAI-124 attenuated pulmonary fibrosis-induced pulmonary artery remodeling." (PMID 36671504, 2023).
pulmonary fibrosis (continued). "Daily intraperitoneal administration of JSI-124 (1 mg/kg) from day 14 to 28 reduced JAK2 and STAT3 phosphorylation as well as the increased protein levels and cell numbers in BAL, lung mass and protein, and expression of IL-6 and IL-13 secondary to lung fibrosis." (PMID 29409529, 2018). "JAK2, once activated, recruits and phosphorylates STAT3 which dimerizes and translocates into the nucleus where it activates the transcription of several genes involved in the fibrotic response like IL-6 family of cytokines, which signal through STAT3, may also contribute to lung fibrosis." (PMID 37626373, 2023). "Previous studies have reported the pro-fibrotic activity of JAK2 and STAT3 in pulmonary fibrosis, but the involvement of JAK1 has not been well studied." (PMID 36903446, 2023).
thrombophilia (36 papers, 2013 to 2025). A condition characterized by an abnormally high level of thrombi. "This case report also reiterates the importance of ensuring that appropriate hematology input is sought early and that thrombophilia screening, including testing for JAK2 mutation, is performed whenever a patient presents with benign PVT and a healthy liver." (PMID 40792243, 2025). "For this reason, a thrombophilia study was carried out (including testing for the factor-V-Leiden mutation, the G20210A prothrombin gene mutation, the JAK 2 mutation, protein C and S deficiency, and antithrombin deficiency), which was negative in all patients." (PMID 39337086, 2024). "•JAK2-mutant CHIP confers a greater risk of VTE than heterozygous thrombophilia but is present at a lower frequency in the general population." (PMID 39102652, 2024). "Only Factor V Leiden and prothrombin mutation was documented for the systemic VTE patients in MATS, whereas a full thrombophilia panel with eight tests including JAK2 mutation was available for 74% in the MVT cohort." (PMID 30756343, 2019). "This case report also reinforces the importance of ensuring that appropriate hematological information is obtained early and that thrombophilia screening, including testing for JAK2 mutation, is performed whenever a patient presents with benign PVT and a healthy liver." (PMID 39925824, 2024). "JAK2 mutations were highly associated with both prevalent and incident VTE risk, with an OR of 6.58 (95% CI, 2.65-16.29; P = 4.7 × 10–5) and a HR of 4.2 (95% CI, 2.18-8.08; P = 1.7 × 10–5), respectively, consistent with the thrombophilia associated with JAK2-mutant MPN." (PMID 39102652, 2024). "On the contrary, somatic JAK2 mutations were much rarer than the major inherited thrombophilias." (PMID 39102652, 2024). "Hence, the JAK2 mutation and the presence of additional thrombophilic markers, such as thrombophilia status, predispose patients with MPN with thrombocythaemia to thrombosis." (PMID 36611455, 2023). "Moreover, thrombophilia tests (including testing for the factor-V-Leiden mutation, the G20210A prothrombin gene mutation, the JAK 2 mutation, protein C and S deficiency, and antithrombin deficiency) were carried out after the diagnosis of PVT and were negative." (PMID 39337086, 2024). "Their study revealed that Jianpi Qingre Tongluo Prescription prevents inflammation and hypercoagulability in GA by inhibiting circRNA 104633 and the JAK2/STAT3 pathway, thereby supporting the development of therapeutic targets and drugs for GA." (PMID 41311848, 2025). "A thrombophilia screen, JAK2, and lupus anticoagulant were checked by hematology as part of outpatient investigations." (PMID 39469279, 2024). "We report a rare case of rapid progressive cognitive decline and limb weakness diagnosed with CVT and multiple intracranial hemorrhage caused by JAK2 V617F mutation-positive PMF, which led to systemic hypercoagulability." (PMID 32846801, 2020). "The patient’s normal thrombophilia workup and absence of acquired risk factors reinforce JAK2 V617F as the primary thrombotic driver, with broader implications for hematologic cancers, and cardiovascular diseases." (PMID 40605890, 2025). "The absence of other thrombophilias (normal antiphospholipid antibodies, protein C/S, factor V Leiden, and JAK2 mutations) further isolates MTHFR-related hyperhomocysteinemia as the primary contributor." (PMID 40115704, 2025). "Based on these findings, screening for the Jak2 mutation as part of routine thrombophilia testing seems reasonable for patients with SVT, but not for those with VTE at other sites." (PMID 41567421, 2025). "In the current study, JAK2 mutation was found to be prevalent in 28/100 (28%) of cases with idiopathic PVT and secondary causes (cases with another factor mutation or acquired risk factors for thrombophilia) were about 72/100 (72%) of while cases." (PMID 33507708, 2021).
thrombophilia (continued). "Thrombophilia testing (including AT, PS & PC, F5 G1691A (FV Leiden)/F2 (prothombin G20210A) genotypes, homocysteine, antiphosphlipid antibody, paroxysmal nocturnal haemoglobinuria by flow cytometry and Janus Kinase-2 (exon 14)) were normal." (PMID 27812779, 2017). "Herein; we present a case of portosplenic vein thrombosis in a primary renal transplant recipient with JAK2 V617F mutation who had no history of prior venous thromboembolism or thrombophilia." (PMID 23876158, 2013). "The hematology findings did not reveal any specific causes of inherited or acquired thrombophilia, although the patient had a Janus kinase 2 (JAK2) mutation, which may increase the risk of thrombosis." (PMID 40792243, 2025). "The result of the thrombophilia examination was negative for inherited or acquired thrombophilia, with the exception of mutation of Janus kinase 2, which may increase the risk of thrombosis." (PMID 40792243, 2025). "The result of thrombophilia examination was negative for inherited or acquired thrombophilia, except for a Janus kinase 2 mutation, which may increase the risk of thrombosis." (PMID 39925824, 2024). "Hematological findings did not reveal any specific causes of inherited or acquired thrombophilia, although the patient had a Janus kinase 2 (JAK2) mutation that may increase the risk of thrombosis." (PMID 39925824, 2024). "Therefore, testing for the JAK2 V617F mutation was not mandatory in patients with unexplained thrombophilia in the country except for those who had thrombosis in uncommon sites or having abnormal cell counts suggestive of MPN." (PMID 36611455, 2023). "Finally, JAK2 and CALR mutations were not performed in all patients as these tests were later included in the thrombophilia workup." (PMID 32878264, 2020).
Cerebral ischemia (35 papers, 2017 to 2026). Restriction of arterial blood supply to the brain associated with insufficient oxygenation to support the metabolic requirements of the tissue. "Cerebral ischemia causes activation of the Jak2 signaling pathway, which is closely related to the occurrence of poststroke brain injury." (PMID 34943061, 2021). "Dex pretreatment alleviated cerebral ischemia/reperfusion injury by inhibiting neuroinflammation through the JAK2/STAT3 pathway." (PMID 38364236, 2024). "Previous research has shown that pharmacological inhibition of the JAK2/STAT3 pathway can reduce inflammatory response after cerebral ischemia and exert neuroprotective effects." (PMID 38137105, 2023). "EP was also found to attenuate the abnormal activation of the JAK2/STAT3 signaling pathway after cerebral ischemia, indicating the potential significance of the JAK2/STAT3 pathway in the neuroprotective effects of EP." (PMID 37143406, 2023). "For instance, resveratrol has a neuroprotective effect against cerebral ischemia/reperfusion injury by up-regulating the expression of p-JAK2, p-STAT3, p-AKT, p-mTOR, and Bcl2, and down-regulating the expression of cleaved caspase-3 and Bax." (PMID 36940077, 2023). "Increasing studies have demonstrated that the JAK2/STAT3 signaling pathway is activated immediately after cerebral ischemia, plays a pivotal role in microglia activation, and acts as a potential therapeutic hotspot in neuroinflammation and neuronal apoptosis." (PMID 37143406, 2023). "Previous studies have suggested that JAK2/STAT3 is closely related to cerebral ischemia and can be activated during the early stages of cerebral infarction." (PMID 36446389, 2022). "Among the surrogate candidates, the Jak2 signaling pathway is crucial in cerebral ischemia cell adaption and death." (PMID 34943061, 2021). "The Jak2 inhibitor AG490 has been used in investigations of cerebral ischemia to explore the role of IL-6." (PMID 34943061, 2021). "This study aimed to investigate the roles of Jak2 in poststroke inflammation and metabolic abnormality in a rat model of permanent cerebral ischemia." (PMID 34943061, 2021). "Conversely, the activation of the Jak2 signaling pathway is also pivotal in the cerebral ischemia neuroprotective actions of melatonin, resveratrol, leptin, and erythropoietin derivatives." (PMID 34943061, 2021). "Many lines of evidence have indicated that JAK2/STAT3 signaling is activated in the early stage of cerebral ischemia and mediates oxidative stress, the inflammatory response, and neuronal apoptosis." (PMID 33790691, 2021). "In this study, the blockade of potential IL-6/Jak2 signaling was produced through the intraperitoneal introduction of AG490 30 min prior to cerebral ischemia." (PMID 34943061, 2021). "In our study, rats with cerebral ischemia exhibited increased IL-6 expression and Jak2 downstream Stat3 protein phosphorylation in the injured cortical tissues, livers, and gastrocnemius muscles." (PMID 34943061, 2021). "Recent studies showed that inhibition of Cx43 hemichannels alleviated cerebral ischemia via the toll-like receptor (TLR4) or JAK2/STAT3 pathway." (PMID 32982919, 2020). "Many previous studies are agree with that the activation of the JAK2/STAT3 pathway attenuates brain ischemia/reperfusion injury." (PMID 31827699, 2019). "In the present study, astrocytic p-STAT3 and p-JAK2 were up-regulated after cerebral ischemia in vivo and after OGD in vitro." (PMID 29867513, 2018). "The effects of EGB on astrocyte activation, LCN2, p-STAT3, and p-JAK2 expression in the ipsilateral peri-infarct cortical area (-1.7 to -1.9 mm from the bregma) following cerebral ischemia were captured with a laser confocal microscope (Olympus FV1200, Japan)." (PMID 29867513, 2018). "Our results showed that EGB significantly inhibited cerebral ischemia development by downregulating the LCN2-activated JAK2/STAT3 signaling pathway and inhibiting astrocyte proliferation." (PMID 29867513, 2018).